ZNF462 (zinc finger protein 462)
Description:
Zinc finger nuclear factor involved in transcription by regulating chromatin structure and organization. Involved in the pluripotency and differentiation of embryonic stem cells by regulating SOX2, POU5F1/OCT4, and NANOG. By binding PBX1, prevents the heterodimerization of PBX1 and HOXA9 and their binding to DNA (By similarity). Regulates neuronal development and neural cell differentiation.
Synonyms: ZFPIP; KIAA1803; DKFZP762N2316; Zfp462; WSKA
Tractability: PROTAC: UniProt records ubiquitination sites on it; ubiquitination databases record sites on it.
Gene: Protein-coding gene on chromosome 9 (106,862,286 to 107,013,634, forward strand). Ensembl gene ENSG00000148143.
Subcellular location: Nucleus
Subcellular location (Human Protein Atlas): Nucleoplasm
Gene Ontology:
Molecular function: protein binding; DNA-binding transcription factor activity; transcription cis-regulatory region binding
Biological process: regulation of DNA-templated transcription
Cellular component: nucleoplasm; nucleus
Genetic constraint (gnomAD): Loss-of-function variants: 10 observed, 207.32 expected, observed/expected ratio (o/e) 0.0482, 90% interval 0.029 to 0.082. The upper end of that interval is the gene's LOEUF score, 0.082, which puts it in group 1 of 6, group 1 being the genes least tolerant of losing a copy. Missense variants: 2,523 observed, 3,331 expected, observed/expected ratio (o/e) 0.76, 90% interval 0.73 to 0.78. Synonymous variants: 1,225 observed, 1,261.2 expected, observed/expected ratio (o/e) 0.97, 90% interval 0.93 to 1.02.
Gene-disease validity (ClinGen):
ClinGen rates the evidence that ZNF462 causes each of these diseases.
Weiss-Kruszka syndrome (autosomal dominant): Definitive.
Homologues: Orthologues: chimpanzee ZNF462 (99% identical), macaque ZNF462 (99% identical), guinea pig ZNF462 (96% identical), pig ZNF462 (95% identical), rabbit ZNF462 (95% identical), dog ZNF462 (94% identical), rat Zfp462 (93% identical), mouse Zfp462 (93% identical), tropical clawed frog znf462 (68% identical), zebrafish ZNF462 (30% identical), Caenorhabditis elegans ztf-16 (4% identical), Caenorhabditis elegans sdz-12 (3% identical), and 2 more. Paralogues in human: ZNF521 (11% identical), ZNF423 (11% identical), ZNF445 (8% identical), ZNF786 (5% identical), ZNF211 (4% identical), ZBTB39 (4% identical), ZNF597 (3% identical).
Diseases named in the same sentence as ZNF462 in open-access papers:
ZNF462 is named in the same sentence as 17 diseases in open-access papers, as found by Europe PMC text mining. Sharing a sentence is not in itself a finding about the gene and the disease. The quoted sentences say what the papers report.
developmental delay (2 papers, 2021). "Recently, Weiss and Kruszka reported a series of patients with developmental delay, distinct craniofacial phenotypes, and hearing loss and showed that this syndrome is due to loss-of-function ZNF462 mutations or microdeletions in the 9q31.2 area." (PMID 33909591, 2021). "ZNF462 haploinsufficiency was consistent with the patient’s Weiss–Kruszka syndrome (craniofacial phenotype, developmental delay, and sensorineural hearing loss), but did not explain his KS." (PMID 33909591, 2021).
pancreatic cancer (2 papers, 2022 to 2023). "ZNF462 may be the target of miR‐210,59 which could be induced by hypoxia‐inducible factor‐1alpha in pancreatic cancer." (PMID 35735060, 2022). "Its impact on downstream target genes like E2F3, EFNA3, GIT2, MNT, ZNF462, HOXA9, and EGR3 underscores its significance in shaping the aggressive phenotype of pancreatic cancer cells." (PMID 38132457, 2023).
Weiss-Kruszka syndrome (2 papers, 2021 to 2022). "Weiss-Kruszka syndrome (WSKA) is a rare disease most often caused by mutations in the ZNF462 gene." (PMID 36568367, 2022).
Headache (1 paper, 2022). Cephalgia, or pain sensed in various parts of the head, not confined to the area of distribution of any nerve. "Of the genes at these loci, six (FAF1, TMX2-CTNND1, AARSD1, PLCD3, ZNF652, and C20orf203; headache-TSH) and six (HMGB1P45, RPL30P1, ZNF462, TMX2-CTNND1, ITPK1, SECISBP2L; headache-fT4) were significant in our gene-based analysis (pFisher’s combined p-value < 2.09 × 10−6)." (PMID 36672757, 2022).
lung carcinoma (1 paper, 2021). "They identified further SNPs, rs6441286 in the IL12A-AS1 gene and rs17723637 in the ZNF462 gene, associated with lung cancer risk (OR = 1.24, p = 6.96 × 10–7 and OR = 1.37, p = 3.49 × 10–7, respectively)." (PMID 33800294, 2021).
migraine (1 paper, 2022). "Interestingly, some of these loci mapped to genes including ITPK1, ZNF462, RPL30P1, ANKDD1B, THADA, ZNF652, and C20orf203 that have been reported as genome-wide significant in the most recent migraine GWAS." (PMID 36672757, 2022).
ovarian carcinoma (1 paper, 2022). A malignant neoplasm originating from the surface ovarian epithelium. "For the first time, we report the immune‐related mutations of ZNF462, ADGRV1 and FLG2 in ovarian cancer." (PMID 35735060, 2022).
senile osteoporosis (1 paper, 2026). "By uncovering a previously unknown ZNF462-MOZ-RUNX2 axis, this work provides a molecular basis for understanding the development of senile osteoporosis." (PMID 41992429, 2026).
Wiedemann-Steiner syndrome (1 paper, 2024). Wiedemann-Steiner syndrome is a rare genetic condition characterized by distinctive facial features, hairy elbows, short stature, and intellectual disability. "Notably, ZNF462 mutations have been associated with growth hormone deficiency in Wiedemann-Steiner syndrome patients, and investigations in Chinese Simmental beef cattle have linked the ZNF462 gene to body weight traits." (PMID 39736931, 2024).
cancer (3 papers, 2018 to 2020). A tumor composed of atypical neoplastic, often pleomorphic cells that invade other tissues. "hsa-miR-342-3p was negatively correlated with downregulated gene targets such as ZNF462 and NCOA7, and hsa-let-7b/c were anti-correlated with predicted targets KRT5 and GABBR2, with known activities in the cancer pathways." (PMID 32182819, 2020). "The remaining four have no known cancer‐related function (KIAA1109, GPHN, GPR25, ZNF462)." (PMID 30809968, 2019).
ZNF462 also shares sentences with these, for which no sentence is quoted: Branchio-otic syndrome (1 paper); breast carcinoma (1); Joubert syndrome (1); kidney disease (1); Obesity (1); sarcopenia (1); tumor (1).